METAP1D (methionyl aminopeptidase type 1D, mitochondrial)
Description:
Removes the N-terminal methionine from nascent proteins. The N-terminal methionine is often cleaved when the second residue in the primary sequence is small and uncharged (Met-Ala-, Cys, Gly, Pro, Ser, Thr, or Val). Requires deformylation of the N(alpha)-formylated initiator methionine before it can be hydrolyzed (By similarity). May play a role in colon tumorigenesis.
Synonyms: MAP 1D; MetAP 1D; MAP1D; Metap1l
Tractability: Small molecule: a drug acting on it is in phase 2 or 3 trials. PROTAC: its protein half-life has been measured.
Gene: Protein-coding gene on chromosome 2 (171,999,943 to 172,082,432, forward strand). Ensembl gene ENSG00000172878.
Subcellular location: Mitochondrion
Subcellular location (Human Protein Atlas): Vesicles
Gene Ontology:
Molecular function: protein binding; aminopeptidase activity; metalloaminopeptidase activity; metalloexopeptidase activity; initiator methionyl aminopeptidase activity; metal ion binding
Biological process: post-translational protein modification; proteolysis
Cellular component: mitochondrion
Genetic constraint (gnomAD): Loss-of-function variants: 28 observed, 31.09 expected, observed/expected ratio (o/e) 0.9, 90% interval 0.67 to 1.24. The upper end of that interval is the gene's LOEUF score, 1.24, which puts it in group 5 of 6, group 1 being the genes least tolerant of losing a copy. Missense variants: 366 observed, 377.61 expected, observed/expected ratio (o/e) 0.97, 90% interval 0.89 to 1.06. Synonymous variants: 135 observed, 136.28 expected, observed/expected ratio (o/e) 0.99, 90% interval 0.86 to 1.14.
Homologues: Orthologues: chimpanzee METAP1D (99% identical), macaque METAP1D (96% identical), dog METAP1D (95% identical), guinea pig METAP1D (95% identical), pig METAP1D (93% identical), rabbit METAP1D (93% identical), mouse Metap1d (91% identical), tropical clawed frog metap1d (78% identical), rat Metap1d (67% identical), zebrafish metap1d (66% identical), Drosophila melanogaster CG5188 (44% identical), Caenorhabditis elegans app-1 (16% identical), and 1 more. Paralogues in human: METAP1 (41% identical), XPNPEP1 (21% identical), XPNPEP2 (19% identical), PEPD (18% identical), XPNPEP3 (17% identical), PA2G4 (16% identical), METAP2 (15% identical).
Diseases named in the same sentence as METAP1D in open-access papers:
METAP1D is named in the same sentence as 10 diseases in open-access papers, as found by Europe PMC text mining. Sharing a sentence is not in itself a finding about the gene and the disease. The quoted sentences say what the papers report.
colon cancer (3 papers, 2013 to 2023). "Reduced expression of MetAP1D by shRNA has been shown to decrease the ability of colon cancer cells to grow in soft agar, indicating that overexpression of MetAP1D may be necessary for tumorigenesis." (PMID 37511988, 2023). "MetAP1D is overexpressed in colon cancer cells and colon tumors." (PMID 37511988, 2023). "Furthermore, each type of MetAP can include different sub-families, such as the human MetAP-1D, also called MAP1D, which is a sub-family of type 1 and is overexpressed in colon cancer." (PMID 31861936, 2019).
autism (1 paper, 2014). Persistent deficits in social interaction and communication and interaction as well as a markedly restricted repertoire of activity and interest as well as repetitive patterns of behavior. "There is some evidence for an association between a linkage block at 2q31.1 containing METAP1D and autism, whilst copy number variants encompassing SFI1 have previously been identified in autism and related developmental disorders." (PMID 24602487, 2014).
dementia (1 paper, 2025). Loss of intellectual abilities interfering with an individual's social and occupational functions. "The other 4 proteins (APOE, PDE5A, METAP1D, and TIMD4) were associated with either dementia or stroke with consistent effects as the MR analysis." (PMID 39818967, 2025).
Leber hereditary optic neuropathy (1 paper, 2023). Leber's hereditary optic neuropathy (LHON) is a mitochondrial neurodegenerative disease affecting the optic nerve and often characterized by sudden vision loss in young adult carriers. "In addition, a mutation in the MetAP1D gene was identified as one candidate involved in the penetrance of Leber’s hereditary optic neuropathy (LHON)." (PMID 37511988, 2023).
cancer (2 papers, 2013 to 2023). A tumor composed of atypical neoplastic, often pleomorphic cells that invade other tissues. "Additionally, there were DMRs overlapping with the gene bodies of METAP1D, RGPD8, and PKP3, which have been shown to be up-regulated in LUAD and promote cancer growth, and whose methylation status has been linked to in utero nicotine exposure." (PMID 37742993, 2023).
METAP1D also shares sentences with these, for which no sentence is quoted: breast carcinoma (1 paper); lung carcinoma (1); spinocerebellar ataxia (1); Stroke (1); tumor (1).